CDC42 (cell division cycle 42)
Diseases named in the same sentence as CDC42 in open-access papers (continued):
Sharing a sentence is not in itself a finding about the gene and the disease.
cancer (continued). "In conclusion, this is the first study to detect activated Rac and Cdc42 in human cancer FFPE tissues using the R-IHC system." (PMID 35110666, 2022). "The active form of RAS, RAC1, and CDC42 has been reported to facilitate the acquisition of various cancer hallmarks, notably proliferation, migration, invasion, and metastasis via upregulation of EMT." (PMID 33758996, 2022). "This is consistent with previous reports highlighting the role of Cdc42 in actin polymerization and cell protrusion in cancer cells." (PMID 34958986, 2022). "Although Cdc42 is first found in yeast, where it plays an important role, it is equally important in the occurrence and development of various human malignant tumors." (PMID 35154449, 2022). "The small GTPase Cdc42 is an integral component of the cytoskeleton, and its dysregulation leads to pathophysiological conditions, such as cancer." (PMID 36253497, 2022). "Cdc42‐mediated filopodia formation is important for cancer cell migration, and dysregulated guanine nucleotide exchange factors (GEFs) Etc2 and Trio impact on Cdc42 and Rac1 activity, respectively." (PMID 33960104, 2022). "Of note, in TMA samples from 33 patients, we demonstrated positive correlations between Rac/Cdc42 activity of cancer cells and clinicopathological factors such as lymphatic vessel invasion." (PMID 35110666, 2022). "It is assumed that Cdc42 activation induces the formation of filopodia and invadopodia to promote cancer progression by enhancing the acquisition of migratory and invasive properties in tumor cells." (PMID 35869555, 2022). "Hypoxia increased the expression of Cdc42, Rac1, and RhoA in human cancer cells and microvascular endothelial cells." (PMID 35154449, 2022). "It is important to determine the activation status of Rac and Cdc42 in cancer tissues for the prediction of metastasis and patient prognosis." (PMID 35110666, 2022). "A recent study also showed that ADAMTS1 decreases cancer migration by regulating the spatiotemporal dynamics of Cdc42 activity." (PMID 35625488, 2022). "The increased expression of Cdc42 can promote the proliferation, invasion, and migration of cancer cells, and accelerate malignant progression of cancer." (PMID 35154449, 2022). "Herein, we describe new Rac and Cdc42 inhibitors with unique mechanisms and varying potency in different cancer cell lines." (PMID 36861094, 2022). "Taken together, eIF3a accelerates the acquisition of the migratory phenotype of cancer cells by activating Cdc42 and RhoA expression at the translational level." (PMID 35300416, 2022). "MiR-216a-5p has been investigated as a tumor suppressor in many cancers 23-26, and miR-216a-5p can negatively regulate the expression of CDC42 27, which was involved in cell growth and migration 28-30." (PMID 35399723, 2022). "The R-IHC technique using a GST-PAK probe easily and rapidly enables the detection of activated Rac and Cdc42 in FFPE tissues, which contributes to realizing special activation of Rac/Cdc42 in cancer tissues." (PMID 35110666, 2022). "A bioinformatics analysis through TIMER online web tool with default settings showed significantly increased messenger (m)RNA levels of CCNB1/CDC42/MAPK7/CD44 in pan cancers, including GBM tumor tissues compared to normal tissues from TCGA)." (PMID 35008426, 2022). "The (GEF) Asef2 has been shown to increase RAC and CDC42 expression, resulting in enhanced cancer cell migration and metastasis." (PMID 35433481, 2022). "We identified significantly increased mRNA levels of the CCNB1/CDC42/MAPK7/CD44 oncogenes in pan cancers, including GBM tumor tissues compared to normal tissues from TCGA, using the TIMER bioinformatics tool." (PMID 35008426, 2022).
cancer (continued). "CDC42 has emerged as a key player in cancer metastasis due to its roles in regulating cell division and actin cytoskeletal rearrangements." (PMID 36146640, 2022). "Targeting the related GTPases Rac and Cdc42 that regulate cancer metastasis is a viable strategy to impede metastasis of solid cancers." (PMID 36861094, 2022). "A substantial number of cancer-associated point mutations in predominantly RAC1, RHOA, and CDC42 have been found and characterized." (PMID 35454871, 2022). "Here we discuss the role of Cdc42 in promoting metastasis, invasion, epithelial-mesenchymal transformation and angiogenesis in malignant tumors." (PMID 35154449, 2022). "Cell division control protein 42, or Cdc42, is a Ras superfamily GTPase is involved in many cellular activities, including cell–cell interaction and cancer progression." (PMID 36012131, 2022). "The more plausible explanation for the apparent protective effect of CDC42 is that CDC42 maintains epithelial polarity and hence protects against cancer initiation." (PMID 35087170, 2022). "Amongst the Cdc42 GEFs, many Dbl family members are altered in cancers, for example Ect2, Tiam-1, Trio, P-Rex1–2 and Vav1–3." (PMID 34196668, 2021). "Exerted anti-cancer activities by aggravating mitochondrial impairment and ER stress through EphB4/CDC42/N-WASP signaling." (PMID 34026649, 2021). "BVES, as a novel regulator of the Rac1 and Cdc42 signaling cascades, controls cell shape and movement in multiple cancers, including pancreatic cancer." (PMID 33731794, 2021). "Our data showed that in controlling collective cancer polarization, the Golgi apparatus pathways predominate over the Rac1/Cdc42 signaling pathways." (PMID 33499191, 2021). "Cdc42 and other components of its signalling pathways therefore represent potential targets for cancer therapeutics." (PMID 34100887, 2021). "Future directions: Assessing the individual biological effects due to Cdc42 inhibition and therefore the contribution of Cdc42 to regulating migration and invasion in cancer requires further advances in selectivity." (PMID 34100887, 2021). "The activation of RhoA, Rac1/2/3 and cdc42 small GTPases exerts an important molecular switching effect on cancer cell proliferation, migration, and invasion." (PMID 34345201, 2021). "Based on experimental and clinical evidence, Rac1 and Cdc42 have been investigated as potential targets for development of cancer therapeutics." (PMID 33413202, 2021). "Depletion of SH3Bp1 has previously been linked to a loss of spatial control of Cdc42 activity in epithelial junction formation and enhanced growth of filopodia, linking this Cdc42 GAP to increased cancer cell migration." (PMID 34196668, 2021). "As a chemokine that mediates tumors, CDC42 can participate in the migration and invasion of various cancer cells." (PMID 33152231, 2021). "Like Ras, Cdc42 and other components of the signalling pathways it controls represent important potential targets for cancer therapeutics." (PMID 34100887, 2021). "ZCL278 thus provided a useful tool for research of the Cdc42 subclass of Rho GTPases in human pathogenesis, such as those of cancer and neurological disorders." (PMID 34054432, 2021). "It is noteworthy that the PAKs are downstream effectors of small GTPases Rac1 and Cdc42 and are overexpressed in a wide variety of cancers." (PMID 34138895, 2021). "We will focus in particular on five members of the RHO GTPase family, including RHOA, RHOB, RHOC, RAC1, and CDC42, to illustrate the role of lncRNAs in cancer progression." (PMID 34771549, 2021). "ML-141 (Cdc42 inhibitor) was toxic at concentrations ≥ 30 μM in cancer cells and at 50 μM in endothelial cells." (PMID 34200503, 2021). "The role of Cdc42 in cancer is well established but the molecular details of its action are still being uncovered." (PMID 34196668, 2021).
cancer (continued). "MiR-20a/miR-106a promotes the loss of WTX, which impairs the interaction between CDC42 and Rho-GDIα, and therefore promotes CDC42 activation, which contributes to cancer progression." (PMID 33406731, 2021). "While relatively few alterations to Cdc42 itself have been documented in cancer, changes to its activators, the RhoGEFs, are widely seen." (PMID 34196668, 2021). "Here we review alterations found to Cdc42 itself and to key components of the signal transduction pathways it controls in cancer." (PMID 34196668, 2021). "Numerous studies have shown that CDC42 functions as a tumor promoter in various cancers and influences proliferation, motility, polarity, growth and drug resistance." (PMID 33380242, 2021). "Compared with ZCL278, ZCL367 has emerged as a bona fide and selective Cdc42 inhibitor with nanomolar potency that suppressed cancer cell development." (PMID 34054432, 2021). "Cdc42 and its relevant signaling pathways were also widely studied as target of small molecules and microRNAs in cancer." (PMID 33726765, 2021). "Another example is represented by VEGFR blocking, which goes along with changes in the subcellular localization of CDC42 which contribute to the control of the cancer." (PMID 33406731, 2021). "Cdc42 has been shown to regulate cell behaviors in cancers that promotes filopodia formation and cell migration." (PMID 34383763, 2021). "In sum, these results uncover a mechanism utilized by NDRG1 to regulate CDC42 activity in coordinating cytoskeleton reorganization, which was crucial in cancer invasion." (PMID 33994856, 2021). "RAC1 and Cdc42 GTPases are key signaling intermediates with important roles in cancer initiation and progression, and inhibitors of these proteins, including EHT1864, have shown promising preclinical efficacy." (PMID 33603169, 2021). "Suggested as a cancer biomarker, a recent publication indicated that the concomitant expression of CDC42 and CACNA2D2 shows improved power as CDC42 alone, in the context of CRC diagnosis." (PMID 33406731, 2021). "Future directions: There is more to understand of the contribution of Cdc42 to the mechanisms of cancer cell migration, invasion, stromal and ECM regulation." (PMID 34196668, 2021). "Cdc42 was also described as a key mediator in the regulation of several types of human cancers, such as gastric cancer and cervical cancer, induced by microRNAs." (PMID 33726765, 2021). "Despite the role of CDC42 within tumor cells in general and IECs in the context of CRC, little is known about immune cells and other cells within the tumor microenvironment and CDC42-mediated regulation of their functions in cancer." (PMID 33406731, 2021). "Prior study suggested CDH3 promoted the activation of β‐Pix/CDC42 axis through collagen fibre orientation to facilitate directional collective cell migration, which was crucial for cancer metastasis." (PMID 34013637, 2021). "Rho-family GTPases, including Ras-related C3 botulinum toxin substrate 1 (Rac1) and cell division control protein 42 (Cdc42), are important modulators of cancer-relevant cell functions and are viewed as promising therapeutic targets." (PMID 33413202, 2021). "Inhibition of Cdc42 and components of its signalling pathways are therefore attractive therapeutic targets in cancer and are currently the subject of small molecule and biologic based targeting efforts, which we have recently reviewed." (PMID 34196668, 2021). "Collectively, we conclude that the Golgi apparatus pathways, instead of the Rac1/Cdc42 signaling pathway, are likely to play a more effective role in regulating the collective polarization of carcinoma cells." (PMID 33499191, 2021). "Recent evidence has demonstrated that CD147 is involved in the invasion program of cancer cells through the activation of CdC42, a RhoGTPase involved in cell polarity, migration and actin cytoskeleton organization." (PMID 31973205, 2020).
cancer (continued). "This review will focus on the close homologs Rac and Cdc42, which have been established as drivers of metastasis and therapy resistance in multiple cancer types." (PMID 32322580, 2020). "ML141, a Cdc42 inhibitor, was also effective in reducing Ser2P and Ser5P levels in both cancer cell lines, except that the difference in Ser5P between control and ML141 was only marginal in HeLa cells." (PMID 32143485, 2020). "The Rho family GTPases Rho, Rac, and Cdc42 have emerged as key players in cancer metastasis, due to their essential roles in regulating cell division and actin cytoskeletal rearrangements; and thus, cell growth, migration/invasion, polarity, and adhesion." (PMID 32322580, 2020). "There have been several excellent studies for exploring the therapeutic potentials of various natural products for their role in inhibiting cancer cells migration and function via regulating the Rac1/2 and Cdc42." (PMID 32578854, 2020). "Our results suggest that Rac1 and Cdc42 GTPase signaling in cultured human cancer cells similarly modulates the CTD Ser2 and Ser5 phosphorylation status." (PMID 32143485, 2020). "Small Rho GTPases including RhoA, Rac1, and Cdc42 are well known to regulate cell migration, and overexpression of these molecules in human cancer correlates with cancer progression." (PMID 32802134, 2020). "Such reorganization, essential for cell motility, is regulated by Rho family of small GTPases (mainly Rho, Rac and Cdc42) which are over expressed in many types of cancer cells." (PMID 32179816, 2020). "Of the Rho GTPases, Rac and the close homolog Cdc42 are central regulators of cancer cell migration and invasion, and thus, metastasis." (PMID 32322580, 2020). "Mitosis can drive cancer cell internalisation through entosis and is linked to the cell division control protein 42 homolog (CDC42), a small dimeric GTP-ase of the Rho family, which is overexpressed in several cancer types." (PMID 32883000, 2020). "This review will summarize the current knowledge on the GEFs that contribute to cancer malignancy and discuss therapies targeting the interaction of oncogenic GEFs with Rac and Cdc42." (PMID 32322580, 2020). "Rho GTPases (RhoA, Rac1, and Cdc42) have been studied in connection with breast carcinogenesis, as well as in connection with other cancers, for many years." (PMID 32443784, 2020). "In other cancers, in contrast, miR-18a negatively regulates CDC42 and SREBP1 to suppress cancer cell proliferation, invasion, and metastasis." (PMID 32967226, 2020). "Activation of the P2X7R also importantly modified cancer cell morphology and triggered the acquisition of a more aggressive phenotype, characterized by activation of Cdc42 Rho-GTPase, remodelling of F-actin, elongation of cells and formation of filopodia." (PMID 32825056, 2020). "The results reported here suggest differential regulation of CTD phosphatases by Cdc42 and Rac1 in human cancer cell culture." (PMID 32143485, 2020). "Previous literature has demonstrated that the Cdc42/N-wasp axis influences F-actin assembly and cell invasion in several types of cancer." (PMID 32843668, 2020). "We provided pharmacological and genetic evidence showing a similar Pol II CTD code modulation by Cdc42 and Rac1 GTPases in cultured human cancer cells." (PMID 32143485, 2020). "The most studied Rho GTPases in oncogynecology are RhoA, RhoC, Rac1, and Cdc42, which show higher expression correlating with the advancement of the cancer." (PMID 32443784, 2020). "We will also briefly discuss the burgeoning relevance of blocking Rac and Cdc42 to overcome cancer therapy resistance." (PMID 32322580, 2020). "Several members of the Rho family of GTPases have been in the context of cancer angiogenesis, migration, and invasion, most notably RhoA, RhoB, RhoC, RhoG, Rac1, and Cdc42." (PMID 32089990, 2020).
cancer (continued). "Cell division control protein 42 homolog (CDC42) is a member of a small GTPase family associated with cell cycle control and is dysregulated in a variety of human cancers." (PMID 32602849, 2020). "As a first step, we chose to study DOCK4 and DOCK9 among a large family of GEFs, given that DOCK4 and DOCK9 have been demonstrated to respectively activate Rac1 and Cdc42 and that mutations in DOCK4 and DOCK9/Zizimin1 have been found in a number of cancers." (PMID 32143485, 2020). "MBQ-167 is a dual inhibitor of the Rho GTPases Rac and Cdc42 that has shown promising results as an anti-cancer therapeutic at the preclinical stage." (PMID 33076517, 2020). "For example, the downregulation of CDC42 reduces NK cell-mediated killing, allowing cancer cells to escape from the human immune response." (PMID 33288739, 2020). "IQGAP1 stimulates filopodia formation, and promotes cell motility and invasion in mammalian and cancer cells, particularly through the interaction with β-catenin, e-cadherin, and small GTPase, i.e., Cdc42, Rac1, and RhoC." (PMID 32824461, 2020). "The pivotal role of Rac and Cdc42 in multiple cancers has been extensively reviewed by us and others." (PMID 32322580, 2020). "Low doses of berberine derived from Coptidis rhizome inhibited Rho GTPase including RhoA, Cdc42, and Rac1 and cell migration in different human cancer cells." (PMID 32443784, 2020). "The product of the CDC42bpα gene exhibits serine-threonine kinase activity and binds to cell division control protein 42 (CDC42), which is a member of the Rho-GTPase protein family that exhibits expression changes in several carcinomas." (PMID 32438542, 2020). "CDC42 is a Rho GTPase and a key regulator in cancer growth, proliferation, survival, and in metastasis." (PMID 30717410, 2019). "CDC42 has been reported to contribute to cancer progression by participating in cell cycle to induce cell proliferation in various cancers." (PMID 31889909, 2019). "For instance, PAKs participates cancer cell proliferation, motility, cell death and anti-cancer drugs resistance, as well as Cdc42/Par/PKC complex affects morphogenesis and cell polarity." (PMID 30754684, 2019). "CDC42 effectors play a critical role in different cancers, either by activating or inhibiting signaling pathways which regulate cell proliferation." (PMID 30717410, 2019). "Three GTPases, RAC, RHO, and Cdc42, play essential roles in coordinating many cellular functions during embryonic development, both in healthy cells and in disease conditions like cancers." (PMID 31027363, 2019). "Taking as a whole, evidence indicates that activation of Cdc42 participates in the progression of cancer cell proliferation, survival, invasion, and migration under hyperglycemic condition." (PMID 30621321, 2019). "In EOC, cytoplasmic p120ctn regulates the activation of the Rho GTPases RhoA, Rac1 and Cdc42, which are known to be essential modulators for cell migration and invasion and consequently promoting cancer cell motility and invasion." (PMID 30795761, 2019). "CDC42 has been shown to play an important role in cancer cell migration and filopodia formation in various human cancers cells." (PMID 30717410, 2019). "When cultured under stiff mechanical environment, Cdc42 translocated from cytoplasm to the nucleus in tumor repopulating cells (i.e., cancer cells with stem-like properties)." (PMID 31380367, 2019). "This includes EGLN1, a well described cancer gene involved in regulation of tumor hypoxia, and CDC42, an oncogene involved in cell cycle control." (PMID 30894871, 2019). "GLK directly phosphorylates and activates IQGAP1, resulting in induction of Cdc42-mediated cell migration and cancer metastasis." (PMID 31640697, 2019). "These wide coverage functions of both Cdc42 and its effectors provide ideas for the broad-spectrum anti-cancer drug designs." (PMID 30754684, 2019).